APOA1 (apolipoprotein A1)
Diseases named in the same sentence as APOA1 in open-access papers (continued):
Sharing a sentence is not in itself a finding about the gene and the disease.
Insulin resistance (110 papers, 2010 to 2026). Increased resistance towards insulin, that is, diminished effectiveness of insulin in reducing blood glucose levels. "The cross-sectional design restricts the ability to infer causality between APOA1 rs5069 genotype, insulin resistance, and metabolic disturbances." (PMID 41422312, 2025). "Outside pregnancy, insulin resistance has been related to LDL particle concentrations, and in a cross-sectional design the apoB-to-ApoA1 ratio has been associated with insulin resistance." (PMID 36979405, 2023). "Accordingly, the associations between insulin resistance, ApoB, and ApoA1 resembled the associations between insulin resistance, LDL particle concentration, and HDL particle concentration, respectively." (PMID 36979405, 2023). "Diabetic patients with C allele frequency had greater susceptibility to have an altered lipid profile and ApoA1 levels and insulin resistance than T allele carriers." (PMID 37351102, 2023). "Several studies observed that APOB/ApoA1 was significantly associated with higher odds of MetS and insulin resistance in Chinese population and PCOS patients." (PMID 35909551, 2022). "Second, in addition to reversing cholesterol transport, apoA-1 has antioxidation and anti-inflammation abilities and is associated with insulin resistance." (PMID 36369093, 2022). "Previous studies demonstrated that SNPs located in the APOA1/C3/A4/A5 gene cluster were associated with metabolic syndrome (MetS), insulin resistance, and cardiovascular disease in several ethnic populations." (PMID 26824674, 2016). "Among men, abdominal obesity was associated with increasing age, insulin resistance, lower apoA1, and higher apoB levels." (PMID 21159215, 2011). "Observational studies found that the ApoB/ApoA1 ratio was significantly associated with insulin resistance in non-diabetic subjects and could become an independent predictor of insulin resistance." (PMID 38310324, 2024). "This study aimed to determine the effect of bariatric surgery on auto-antibodies titres against Apolipoprotein A-1 (anti-apoA-1 IgG), looking for changes associated with lipid parameters, insulin resistance, inflammatory profile and percentage of excess body mass index loss (%EBMIL)." (PMID 34888742, 2022). "The apoB100/apoA1 ratio is strongly associated with insulin resistance." (PMID 34162950, 2021). "The ApoB/ApoA1 ratio is strongly associated with insulin resistance." (PMID 24093822, 2013). "Hence, decreased HDL/ApoA1 levels, as observed in the current study, may increase the risk of developing insulin resistance among the Iraqis." (PMID 35927727, 2022). "Reduced APOA1 expression impairs reverse cholesterol transport, directly promoting hepatic lipid accumulation and exacerbating insulin resistance – core pathways in MASLD." (PMID 41056021, 2026). "Beyond its role in HDL-c, APOA1 plays a multifaceted role in anti-inflammation, anti-insulin resistance, anti-atherosclerosis, and other processes." (PMID 40535329, 2025). "Mounting evidence suggests that APOA1 plays multifaceted roles in anti-inflammation, anti-insulin resistance, anti-atherosclerosis, and the inhibition of oxidative stress and nitric oxide production, surpassing the effects of HDL-c itself." (PMID 39764250, 2024). "The findings indicated that TG/APOA1 contributed to being an independent risk factor for MAFLD and holds promise to be a valuable insulin resistance marker for identifying MAFLD." (PMID 39764250, 2024). "Recently, SNPs in APOA1 have been widely utilized as predictive markers for CAD risk, and prospective studies of weight loss in obese patients have shown that the APOA1 (rs670) gene displays significant effects on LDL cholesterol levels and insulin resistance." (PMID 38927431, 2024). "TG/APOA1 serves as an effective index of insulin resistance in identifying MAFLD, offering advantages in the screening of MAFLD in T2DM." (PMID 39764250, 2024).
Insulin resistance (continued). "Beyond its well-documented cardioprotective function, recent research has shown that APOA1 also plays novel roles in mitigating inflammation and insulin resistance in the pathogenesis of NAFLD." (PMID 39764250, 2024). "The APOA1 gene mutation rs670 has been shown to increase HDL-C levels, insulin levels, and the homeostatic model assessment for insulin resistance (HOMA-IR) while simultaneously being associated with decreased insulin resistance." (PMID 37375802, 2023). "On the contrary, HDL enhances insulin resistance and protects against cytokines- or high-glucose-induced apoptosis pancreatic β-cell apoptosis via apolipoprotein A1 (ApoA1)." (PMID 36788551, 2023). "PCOS patients had significantly higher levels of fasting insulin (FINS), hemostasis of model assessment-insulin resistance, low-lipoprotein cholesterol, triglyceride, apolipoprotein B, apolipoprotein B/apolipoprotein A1, and homocysteine than the controls." (PMID 36930082, 2023). "Conversely, TT genotype carriers demonstrated increased levels of HDL-C and ApoA1, lower insulin resistance, serum glucose, LDL-C, and TG levels." (PMID 37351102, 2023). "Increased circulating levels of lipoprotein-A, apolipoprotein-A1, and apolipoprotein-E as a result of insulin resistance in acromegaly leads to disorders of lipoprotein metabolism." (PMID 33389987, 2021). "ApoA1 was further down-regulated under the presence of up-regulation insulin resistance, whereas weight reduction induced its up-regulation." (PMID 25960181, 2015). "Among men, factors were age, apolipoprotein A1 level, apolipoprotein B level, and insulin resistance." (PMID 21159215, 2011). "Generally, participants had low HDL cholesterol, low apoA1, and high triglyceride levels, which typically coexist in people with insulin resistance." (PMID 21159217, 2011). "And the interaction between APOA1 genetic variants and these non-insulin-based insulin resistance surrogates remains largely unexplored." (PMID 41422312, 2025). "Consequently, this study aims to evaluate the correlation between TG/APOA1 and MAFLD, as well as compare the efficacy of TG/APOA1 with other insulin resistance indexes, such as TG/HDL-c and TyG index, in identifying MAFLD among individuals with T2DM." (PMID 39764250, 2024). "Therefore, the TG/APOA1 holds promise to be a more valuable insulin resistance marker for diagnosing MAFLD." (PMID 39764250, 2024). "It is thought that it may represent a better marker than the apoB/apoA1 ratio for identifying insulin resistance and MS in some populations." (PMID 24688542, 2014). "APOA1, APOB, and APOC4 are core members of the apolipoprotein family that play crucial roles in regulating lipid metabolism and insulin resistance." (PMID 41056021, 2026). "Biochemical variables, triglyceride (TG), high‐density lipoprotein cholesterol (HDL‐C), apolipoprotein A1 (ApoA1), apolipoprotein B (ApoB), fasting serum insulin (FINS), and homeostatic model assessment of insulin resistance (HOMA‐IR) were determined." (PMID 41323197, 2025). "In our current research, we did observe the occurrence of metabolic dysfunction in the CPZ group, characterized by insulin resistance and alterations in plasma levels of HDL, ApoA1, and ApoB levels." (PMID 38802393, 2024). "Our previous report showed that serum 4-tOP levels were inversely correlated with insulin resistance, BMI, and CIMT, although positively correlated with favorable lipids (HDL-C, apolipoprotein A1)." (PMID 37755767, 2023). "Similarly, the level of ApoA1 corresponds to the quantity of HDL particles; therefore, apolipoproteins taken individually or the ratio of ApoB and ApoA1 (ApoB/A1 ratio) would theoretically serve as optimal markers of lipid abnormalities associated with insulin resistance and MetS." (PMID 37420190, 2023). "APOA1 and PLTP are members of the PPAR signaling pathway and are closely related to insulin resistance, and glucose and lipid metabolism, and participate in the regulation of thermogenesis." (PMID 36292795, 2022).
Insulin resistance (continued). "ApoA1 is considered a favored alternative to HDL-C in the prediction of cardiovascular diseases, insulin resistance, and DM." (PMID 32717783, 2020). "A recent study found that non-HDL-c/HDL-c was a better indicator than apolipoprotein B (ApoB)/apolipoprotein A1 (ApoA1) and ApoB/LDL-c in identifying MetS and insulin resistance." (PMID 24555711, 2014). "The ApoB/ApoA1 ratio and LDL-C were also reported to be positively correlated with insulin resistance in a Chinese population with abdominal obesity." (PMID 24093822, 2013). "In the ART cohort, the mRNA expression level of SREBP‐1 exhibited a positive correlation with BMI, ApoB, fasting blood glucose, fasting insulin, and the insulin resistance index, whereas it demonstrated a negative correlation with ApoA1." (PMID 41323197, 2025). "Metabolism‐related indicators were mainly monitored in this study including triglyceride (TG), HDL‐C, serum apolipoprotein A1 (ApoA1), serum apolipoprotein B (ApoB), fasting serum insulin (FINS), and homeostatic model assessment of insulin resistance (HOMA‐IR)." (PMID 41323197, 2025). "Overall, PCA results indicate that metabolic variability in both euglycemic and T2DM obese individuals is primarily driven by biochemical and insulin resistance markers, rather than APOA1 genotype." (PMID 41422312, 2025). "Notably, recent evidence suggests that APOA1 plays a pivotal role in linking MAFLD to cardiovascular disease and possesses multifaceted functions in anti-inflammation and anti-insulin resistance, surpassing the influence of HDL-c alone." (PMID 39764250, 2024). "Regarding insulin resistance, numerous studies have established correlation between ApoA1, Apo B and ApoA1/ApoB ratio with insulin resistance in both diabetic and normo-glycemic patients." (PMID 37420190, 2023). "Insulin resistance in our study was not related to either apolipoprotein A1 (ApoA1), the major apolipoprotein in HDL particles, or apolipoprotein B (ApoB), the major apolipoprotein in TG-rich lipoprotein VLDL and LDL." (PMID 36979405, 2023). "At the baseline and at the end of the study, blood glucose levels, homeostatic model assessment of insulin resistance (HOMA-IR) and the homeostatic model assessment of β-cell dysfunction (HOMA-B), as well as apolipoprotein A-I (ApoA1) and apolipoprotein B (ApoB) were measured." (PMID 36788517, 2023). "Circulating endothelin-1 levels were associated with both insulin resistance (HOMA-IR) and apoB/apoA1 ratio in men whereas no such associations were observed in women." (PMID 26573599, 2015). "IRRS and ApoA1 proteome were measured in 858 individuals without DM (Studies of Insulin Resistance at Stanford), revealing correlations between IRRS and multiple proteomic markers and consistent correlations compared to the gold-standard SSPG concentration measurement of IR." (PMID 41226726, 2025). "Studies have proven the NonHDLc/HDLc ratio to be a better predictor for CVD than NonHDLc, as well as a better predictor for insulin resistance and MS than the apoB/apoA1 ratio (difference might be attributed to dysfunctional HDL levels)." (PMID 30131058, 2018). "ApoB showed positive correlation with insulin resistance, but ApoA1, ApoA1/ApoB, LDL-C/ApoB, and HDL-C/ApoA1 revealed inverse results in non-diabetic normoglycemic patients." (PMID 24093822, 2013).
breast carcinoma (74 papers, 2007 to 2026). "The results indicated that serum levels of TC (p = 0.04), HDL-C (p = 0.009), and apoA1 (p = 0.004) were associated with reduced overall risk of breast cancer." (PMID 41594284, 2026). "In patients with breast cancer, the frequency of APOA1 copy number loss in tumor cells is negatively associated with serum ApoA1 levels." (PMID 38212711, 2024). "Among these 112 unique blood metabolites, genetically determined high levels of high-density lipoprotein cholesterol (HDL-C), apolipoprotein A1, and acetate were significantly associated with an increased risk of breast cancer." (PMID 36694207, 2023). "Studies have shown reduced APOA1 expression in the serum of breast cancer patients, and APOA1 gene mutations are linked with an increased risk of developing breast cancer." (PMID 38067270, 2023). "In breast cancer, low expression of APOA1 predicted a higher risk of breast cancer development and recurrence." (PMID 35421932, 2022). "In the METABRIC cohort, APOA1/C3/A4/A5 copy number loss was significantly associated with shorter breast cancer-specific survival in both the univariate analysis (hazard ratio [HR] = 1.33, P = 0.011) and the multivariate analysis (HR = 1.44, P = .007)." (PMID 34226567, 2021). "Our study demonstrated that APOA1/C3/A4/A5 copy number loss was significantly associated with lower survival in patients with breast cancer, although the association was only significant for Western patients." (PMID 34226567, 2021). "A positive association was found between high-density lipoprotein cholesterol (HDL-C) and apoA1 levels with increased breast cancer risk, 23 % and 28 % respectively." (PMID 32577155, 2020). "Among 27 cancer types, low HDL cholesterol and/or apolipoprotein A1 were associated with increased risk of multiple myeloma, myeloproliferative neoplasm, non-Hodgkin lymphoma, breast cancer, lung cancer, and nervous system cancer." (PMID 32998735, 2020). "Many studies showed that expression of APOA1 was inversely associated with development of breast cancer, but in a few studies, higher APOA1 expression was positively associated with promoting breast cancer." (PMID 31573738, 2019). "A prospective case-control study found a positive association between APOA1 -75 A allele carriers and breast cancer risk." (PMID 26173491, 2015). "It has also been found that APOA1 -75 G/A and +83 C/T genotypes were associated with susceptibility to breast cancer and lymph node metastases occurrence, respectively." (PMID 26537097, 2015). "The APOA1 -75 G/A and +83 C/T genotypes were also associated with susceptibility to breast cancer and lymph node metastases occurrence, respectively." (PMID 26537097, 2015). "The frequency of APOA1 rs670 A allele (G/A + A/A) carriers in breast cancer patients was significantly higher than that in healthy controls (59.64% vs. 48.77%, p=0.038)." (PMID 23829168, 2013). "The association of SNP (APOA1 rs670) showing correlation with breast cancer with baseline and follow-up parameters was further examined." (PMID 23829168, 2013). "Despite the significance in increased recurrence risk, the APOA1 rs670 G/A breast cancer carriers had mean survival years comparable to their G/G counterparts." (PMID 23829168, 2013). "A case–control study suggested that a positive association was found between the APOA1 -75 A allele carriers and breast cancer risk." (PMID 24209603, 2013). "A cross-sectional study focusing on the association of APOA1 SNPs with breast cancer and patient phenotype reported that the -75G/A polymorphism correlated with breast cancer risk at baseline." (PMID 23829168, 2013). "APOA1 rs670 A allele carriage was higher in breast cancer patients than controls (59.64% vs. 48.77%, p=0.038)." (PMID 23829168, 2013). "Furthermore, abnormal levels of TC, LDL-C, HDL-C, and apolipoprotein A1 (ApoA1) are closely associated with different molecular subclasses of breast cancer and are correlated with the expression of the Ki-67 protein." (PMID 40666099, 2025).
breast carcinoma (continued). "Furthermore, a postoperative serum proteomics analysis conducted on high-risk breast cancer patients revealed a correlation between low ApoA1 expression and the occurrence of metastatic relapse." (PMID 38566092, 2024). "Our findings suggest that APOA1 rs670 indicate a post-surgery risk of breast cancer disease progression, and that carriers of this SNP may benefit from more advanced disease monitoring and therapy regimens than the current regular standards." (PMID 23829168, 2013). "Genetic variations of APOA1 may also act as a marker for the increased risk of breast cancer." (PMID 26463353, 2016). "Furthermore, control of lipid homeostasis might protect APOA1 rs670 minor allele carriers from breast cancer occurrence and progression." (PMID 23829168, 2013). "The downregulation of APOA1 is linked to increased tumor progression in cancers such as basal-like breast cancer and hepatocellular carcinoma, whereas overexpression of APOA1 has shown anti-proliferative and pro-apoptotic effects." (PMID 40551123, 2025). "In vitro experiments and mouse breast cancer models were utilized to evaluate the molecular mechanism of ApoA1 in regulating cholesterol efflux and inhibiting breast cancer progression and metastasis." (PMID 38566092, 2024). "In our in vitro experiments, we observed that transfecting breast cancer cells with a plasmid overexpressing ApoA1 or infecting them with a lentivirus carrying ApoA1 gene resulted in inhibited migration of breast cancer." (PMID 38566092, 2024). "Further analysis revealed that breast cancer patients with higher expression levels of cholesterol efflux-related genes, such as ApoA1 and NR1H3 (also known as LXRa), appeared to have extended survival rates." (PMID 38566092, 2024). "Further research on the biology and changes in APOA1/C3/A4/A5 genes and other gene alterations in breast cancer cells is warranted." (PMID 34226567, 2021). "APOB, previously identified as a candidate gene related to lipid abnormality, was proved significant in the incidence of CRC and lung cancer while APOA1 was correlated with the incidence of breast cancer." (PMID 34820194, 2021). "In this study, we prepared ApoA1-modified cationic liposomes loaded with doxorubicin and investigated the antitumor efficacy and reversion of multidrug resistance in breast cancer." (PMID 33652957, 2021). "It has been reported that the serum concentration of ApoA1 in breast cancer, colorectal cancer, and pancreatic cancer was lower than that of the control group, which was considered to be a serum marker for detecting carcinoma." (PMID 26646794, 2016). "We analyzed the distribution of 5 selected APOA1/C3/A5 SNPs in recruited Taiwanese breast cancer patients (n=223) and healthy controls (n=162)." (PMID 23829168, 2013). "In this study, we first tested the correlation of 5 selected well-known SNPs on the APOA1/C3/A5 gene cluster with breast cancer in a case–control manner." (PMID 23829168, 2013). "The median recurrence-free and overall survival years of APOA1 rs670 A/A carrying breast cancer patients were both longer than the standard chemotherapy duration (~1 year) and the advised 5-year limit for continuous TAM usage." (PMID 23829168, 2013). "The associations of increased ApoA-1/HDL-C ratio and abdominal obesity had also been reported in untreated newly diagnosed breast cancer patients." (PMID 24093822, 2013). "Though the association of plasma lipid profiles and breast cancer incidence or progression is strongly and continuously suggested, the molecular mechanisms of HDL or apoA1 in promoting breast cancer risk are still unclear." (PMID 23829168, 2013). "We showed that only APOA1 rs670 out of the 5 tested SNPs was correlated to breast cancer, lymph node-positivity, ER/PR double-negativity at baseline." (PMID 23829168, 2013). "Higher proportions of APOA1 rs670 G/A and A/A carrying breast cancer patients developed recurrence or death than G/G carriers." (PMID 23829168, 2013).